CD4 (CD4 molecule)
Diseases named in the same sentence as CD4 in open-access papers (continued):
Sharing a sentence is not in itself a finding about the gene and the disease.
tumor (continued). "In HPV-induced tumors expressing the highly immunogenic E6 and E7 viral Ags, CD39 expression identified HPV Ag-specific CD8 and CD4 tumor-infiltrating lymphocytes (TILs)." (PMID 35954341, 2022). "The involvement of cytotoxic T cells (CTL, CD8+ T cells) and helper T cells (CD4+ T cells) is the most critical factor in tumor immunotherapy." (PMID 35494032, 2022). "Depletion of CD4+ T cells in the blood following antibody treatment was confirmed, followed by subcutaneous tumor inoculation." (PMID 36611881, 2022). "In one patient who showed tumor regrowth 4 months after G47∆ therapy, the high numbers of CD4+ and CD8+ lymphocytes persisted whereas the number of Foxp3+ cells increased." (PMID 35864254, 2022). "For instance, the tumor specimen of patient 1 in our cohort showed significant immune infiltration with substantial amounts of CD4 and CD8 T cells." (PMID 35109850, 2022). "Recently, the identification of a unique lineage of CD4+ T cells, named Treg, with the capacity of suppressing T cell effector function has put a new light on the mechanisms of tumor escape." (PMID 36068484, 2022). "In this work, we show that CD4+ T cells with a cytotoxic phenotype are a notable component of the tumor-infiltrating immune population in NSCLC." (PMID 35831288, 2022). "Our data shows that whereas in the draining lymph nodes, the Tr1 cells subset composes <5% of CD4+ T cells, in the tumor, they reach ∼30% of CD4+ T cells." (PMID 35860556, 2022). "When we compared tumor versus non-tumor samples, we observed a significantly lower percentage of T-lymphocyte infiltration in the tumor in which the CD4+ T-cell density increased compared to the CD8+ T cells." (PMID 36551555, 2022). "One study showed that CD8+, CD4+ T cells, and B cells are positively correlated with the reduction of tumor volume." (PMID 36034656, 2022). "Compared to their blood-derived counterparts, tumor-derived CD4+ effector memory T-cells showed high levels of PD-1 and were functionally fatigued." (PMID 35269652, 2022). "For example, IFN-γ secreted by Th-1 CD4+ and CD8+ cells activates cytotoxic immunity, inhibits tumor growth, and is associated with a reduced risk of relapse in CRC." (PMID 36422171, 2022). "Recent studies have documented that CD4+ T cells are also effective at tumor rejection similar to CD8+ T cells." (PMID 35135586, 2022). "The Wnt ligands secreted by tumour cells activate the transformation of CD4(+) T cells to Treg cells by promoting the expression of β-catenin expressions in DCs, reducing the burden on tumour metabolic burden." (PMID 36578477, 2022). "Lapatinib also has the ability to modulate the TME as it promotes tumour infiltration by CD4 + CD8 + IFN-γ-producing T-cells through a Stat1 dependent pathway." (PMID 35804943, 2022). "Cytotoxic CD8+ T cells kill tumor cells by secreting TNF-α and IFN-γ, while CD4+ T cells produce multiple cytokines to boost anti-tumor immune responses." (PMID 36313283, 2022). "Further analysis of multiple tumor tissue sections indicated that tumors from DC-iMB-treated animals presented a significant increase in CD4+ (2.2–4.3-fold, p < 0.005) and CD8+ T cells (4.3–10.9-fold, p < 0.005) compared to the other groups." (PMID 36224614, 2022). "Although anti-CTLA-4 therapy was initially used to augment the activity of tumor-infiltrating CD8+ T and CD4+ T cells, it has been suggested that this therapy exerts its effects through a cTreg-depleting effect in the tumor site." (PMID 35860556, 2022). "Depletion of CD8+ T cells either alone or in combination with CD4+ T cells completely rescued the tumor-suppressive phenotype of Gata4." (PMID 35017504, 2022).
tumor (continued). "The mechanism of CD4+ T cell exhaustion in malignant tumors and the rescue approaches constitute one of the current hotspots in field of tumor-related research." (PMID 35912251, 2022). "We found that in mice vaccinated with neoantigens, compared to mice treated with poly IC alone, a greater percentage of CD4 T cells expressed high levels of CD11a and CD49d, both in spleen and in tumor." (PMID 36569934, 2022). "FDX1 expression was also highly correlated with the T stage, tumor grade, and CD4+ T cell infiltration in the collected ccRCC samples." (PMID 36611966, 2022). "Tumor biopsies pre- and post-treatment showed increased frequency of activated conventional CD4+ TILs in the majority of patients, which was accompanied by higher oligoclonality in TCRβ sequencing." (PMID 36451828, 2022). "The 6951 single cells included 4371 tumor cells, 90 B cells, 943 macrophages, 185 mastocytes, 102 NK cells, 235 CD4 + T cells, 659 CD8 + T cells, 206 T cells, 79 endothelial cells, and 81 cancer-associated fibroblasts (CAFs)." (PMID 35093080, 2022). "Upon treatment with ExoBlock, T-cell-mediated tumor suppression was significantly enhanced along with an increase in the number and function of CD4 and CD8 T-cells, which are involved in reducing tumor metastasis, thus providing promising antitumor therapy." (PMID 36726968, 2022). "IFN-γ secreted by Th1 CD4+ T cells upregulates MHC I on tumor cells, improving the killing effector of CD8+ T cells." (PMID 35303904, 2022). "In tumor-draining lymph nodes, Tmem176b expression in cDC2 was shown to be supported by regulatory T (Treg) CD4+ cells, suggesting an immunoregulatory role for this cation channels in cDC2." (PMID 36340035, 2022). "Considering the prominent role of CD8+T cells in antitumor effect,33we first analyzed tumor-infiltrated CD3+CD8+CD4-cells." (PMID 35707772, 2022). "In line with the role played by αCTLA-4, we observed a statistically significant induction of a neoantigen-specific CD4+TNFα+ in tumor-bearing mice." (PMID 35110563, 2022). "In the CD4+ T-cell compartment, the regulatory CD4+ Tregs seem to play a major role in immune suppression and tumour resistance." (PMID 35454848, 2022). "At the same time, the results of flow cytometry showed that the number of tumor-infiltrating CD8 positive T cells was significantly higher than that of the control group, along with elevated tumor-infiltrating CD4 positive T cells." (PMID 36536402, 2022). "SFV-IFNγ expression decreased myeloid cell infiltration into the tumour, and led to an increased number of CD4+ and CD8+ and a decrease in Treg cell populations." (PMID 36140243, 2022). "Flow cytometric analyses showed that PF543 treatment significantly induced tumor-infiltrating CD4+ T cells and CD8+ T cells in the TME." (PMID 36050478, 2022). "Another study revealed that the presence of CD4+ T cells correlates with tumor size and aggressive features of TC, while the presence of cytotoxic CD8+ T cells in the TME is associated with a favorable prognosis in patients with PTC." (PMID 36230610, 2022). "Deletion of CD274 (which encodes PD-L1) in T cells enhances adaptive tumour immunity and activates TAMs, indicating that the use of anti-PD-1/PD-L1 inhibitors will enhance immunity in tumours with a high density of CD4+FoxP3−PD-L1+ T cells." (PMID 35982052, 2022). "In fluorescent immunostaining, CD107a+ CD4+ T cells were barely detectable in the tumor centers of HFD-fed mice." (PMID 36611881, 2022). "During tumor cell elimination, effector T cells, including CD4+ helper (Th) and CD8+ cytotoxic lymphocytes (CTLs), secrete cytokines IFN‐γ and TNF‐α to induce tumor cell death and recruit other effector cells." (PMID 35782339, 2022). "TCL6 regulates tumor-associated B cells, CD8 + T cells, CD4 + T cells, neutrophils, and Dendritic cells (DCs)." (PMID 36207500, 2022). "CD4+ T cells have been shown to play a crucial role in tumor progression and clinical treatment of BC patients." (PMID 35603183, 2022).
tumor (continued). "The cells residing in TLS in tumours are known to express Th1, CD4, CD8, CD31, CD23, FOXP3, chemokines (CCL19, CCL21) and clusters of DC-Lamp+ mature dendritic cells providing an immune-supportive niche." (PMID 35355992, 2022). "DCs are the most powerful antigen-presenting cells and bridge the innate and adaptive immune responses by processing tumor antigens and presenting peptides to either CD4+ or CD8+ T cells." (PMID 35720407, 2022). "It is possible that SGT-53 treatment downregulates tumor expression of Tgfb, which is a key regulator of the signaling pathways that initiate and maintain FoxP3 expression and the suppressive function in CD4+CD25− precursors." (PMID 36359830, 2022). "Increased recruitment of tumor-infiltrating CD3+CD4+ T helper cells was also observed following SR717@RGE-HFn NP treatment compared with the other treatments." (PMID 35386310, 2022). "We use single-cell profiling to identify tumor-infiltrating, clonally expanded CD4+ T cells that express a canonical cytotoxic gene program and NSCLC cells with elevated HLA-II expression." (PMID 35831288, 2022). "One of these TNFR2-specific antibodies was also tested for its ability to inhibit CD4 T-cells of Sézary syndrome (SS) patients and various tumor cell lines." (PMID 35681583, 2022). "BHLHE40, another BHLH family member, is highly expressed by TH1-like tumor-infiltrating CD4+ T cells, a population enriched in the microsatellite-instable subtype." (PMID 35806162, 2022). "GDNA combined with targeting of PD-1 and HPV16 E6/E7 dramatically increased the number of dendritic cells, CD8+ and CD4+ T lymphocytes and hampered tumor growth." (PMID 35300341, 2022). "Immunofluorescence assays showed that tumor tissues from mice treated with sh-LINC01123 + miR-214-3p-inhibitor exhibited decreased positive rates of CD4 and CD8 proteins (P < 0.05)." (PMID 35115487, 2022). "Overall, we determined that GNG4 is specifically expressed in exhausted CD4+ T cells in BLCA tumor microenvironment." (PMID 35456499, 2022). "During the chronic development of cancer, induced Tregs (iTregs) arise from naive CD4+ cells in the periphery, infiltrate into the tumor microenvironment and suppress the effector T cells in aspects of cell proliferation and cytokines production." (PMID 35251028, 2022). "Chemotherapy can enhance anti-tumour immunity, including stimulation of CD4+ effector T (Teff) cells and CD8+ Teff cells." (PMID 36159866, 2022). "LAG-3 was significantly upregulated on the surface of tumour-infiltrating CD4+ T cells compared with those in circulation in the treatment-naïve setting and post-FLOT setting (p = 0.01 and p = 0.007)." (PMID 35366537, 2022). "The N2 phenotype of TANs exerts an immunosuppressive action by reducing the anti-tumor response of the CD4+ and CD8+ T lymphocytes." (PMID 36289773, 2022). "While activated CD4+ T helper 2 (Th2) cells and regulatory T (Treg) cells promote tumor-induced immunosuppression, CD4+ T helper 17 (Th17) cells either support or inhibit tumor progression, depending on the context." (PMID 35897036, 2022). "As the dominant immune response in anti-tumor immunity, cellular immune response is mainly composed by T lymphocytes, especially CD4 and CD8 regulatory T lymphocytes." (PMID 35986302, 2022). "CellMinor analysis was employed to explore the relationship between CD4 mRNA expression and the reaction of tumor cells to NAC drugs." (PMID 35433455, 2022). "On the other hand, accumulation of PD-1high CD4 subsets within the tumor correlated with tumor burden, as shown in a clinical study with NSCLC." (PMID 36362027, 2022). "Several studies have now established that both cytolytic CD8+ T (Tc) cells and CD4+ T helper (Th) cells are effective in tumor immunotherapy." (PMID 35203357, 2022). "Strong positive correlations were found between frequencies of FoxP3+ Tregs and FoxP3+Helios+ Tregs with frequencies of various immune checkpoint-expressing CD4+ T cells in the tumor microenvironment (TME)." (PMID 36146549, 2022).
tumor (continued). "In this study, CDKN2A was positively correlated with the infiltration of activated B and CD4 T cells in the tumour microenvironment, leading to a better prognosis of HNSCC." (PMID 36699463, 2022). "Studies on bladder cancer cells indicated that inosine enhanced the function of anti-CTLA-4, causing to increase infiltration of IFN-γ+ CD4+ and IFN-γ+ CD8+ T-cells into the tumour, as well as reducing overall tumour weight." (PMID 36144335, 2022). "CD4+ T-follicular helper cells are a unique anti-tumor immune subset responsible for the activation and maturation of B-cells and B-cell-mediated immunity." (PMID 35267563, 2022). "In the study of tumours and viruses, it has been found that high concentrations of antigens for a long time can induce CD4+T cells to express PD-1, decreases the IFN-γ expression of lymphocytes and lead to immune exhaustion." (PMID 36587204, 2022). "Considering the apparent correlation between the lactate metabolism score and tumor immunity, we analyzed more differences in macrophage and CD4+T cell infiltration between the high and low lactate metabolism score groups for BRCA and THCA." (PMID 35873566, 2022). "Splenic MDSCs were isolated from the treated mice on day 4 after therapy and sorted for coculture with CD4+ T cells from tumor-bearing mice at a ratio of 1:5, and the subsets of CD4+ T cells were analyzed after 24 h." (PMID 36389684, 2022). "ID8-C3 tumors contained the highest frequencies of CD4+ T cells (∼10% of all tumor-infiltrating leukocytes)." (PMID 36311166, 2022). "DCs move to neighboring lymph nodes (LN) during maturation, where they present tumor antigens and activate tumor-specific CD4+ and CD8+ T cells." (PMID 35890239, 2022). "Altogether these findings underscore the importance of CD4 T cells and their ability to maintain a long-term anti-tumor immune response." (PMID 36385142, 2022). "In fact, mutant MHC-II neoepitope vaccine elicited anti-tumor response in CD4+ T cell-dependent manner." (PMID 35269735, 2022). "The major contributing CD4+ T cells in tumor immunology are subdivided into different subsets, that is, Th1, Th2, Th17, and Tregs, based on their secretory cytokines and immunological roles." (PMID 36090972, 2022). "An alternative way tumor site can be enriched in Tregs is the differentiation of tumor-reactive effector CD4+ T cells into pTregs." (PMID 36248808, 2022). "Subsequent in vivo study has shown that LL-37 downregulated the immunosuppressive myeloid-derived suppressor cells and M2 macrophages while upregulated the anti-cancer effectors CD8+ and CD4+ T cells in the tumor microenvironment." (PMID 35935871, 2022). "Tumor-free Lyve-1-KO livers showed increased numbers of CD4+ T cells (P = 0.0094), CD8+ T cells (P = 0.0449), regulatory T cells (Treg) (P = 0.0389) and eosinophils (P = 0.0139) compared to Ctrl livers, whereas other immune cell subtypes remained unchanged." (PMID 36496412, 2022). "The decrease in CD4+/CD8+ ratio suggests suppressed immune levels and the susceptibility to tumor metastasis." (PMID 35769818, 2022). "The increased tumour uptake of [18F]AlF-mNOTA-GZP in TRs was associated with a robust increase in tumour-associated activated T cells, especially GZB+ CD8+ cells, GZB+ CD45+ cells and CD25+ CD4 cells are in line with previously reported data." (PMID 35057046, 2022). "Those lesions exhibited significantly higher densities of tumour microenvironment cellular infiltrate including CD4, FOXP3, CD163 and PDL-1, potentially indicating a role for the inflammatory immune response in disease progression." (PMID 36224403, 2022). "To verify the immune response to the tumor, we evaluated the activation and proliferation in two main effector T-cell subsets: conventional CD4+ T helper (Th) and CD8+ T-cells isolated from LN." (PMID 36555468, 2022). "Remarkably, peripheral CD127low FOXP3+ CD4+ T cells are able to inhibit cytotoxic T cell response, including the tumor-directed one." (PMID 35883486, 2022).
tumor (continued). "The tumor-infiltrating T cells with a larger clonal size were enriched for CD8 expression, whereas CD4 expression was associated with singletons and small clonal size." (PMID 36185254, 2022). "CD3+ T cells dominated in both areas (725 cells/mm2 in the tumor epithelium vs. 719 cells/mm2 in the stroma) but more CD4+ T cells were found intratumorally (p=0.043)." (PMID 36131941, 2022). "We found that tumor-infiltrating leukocytes, including macrophages M0/M1/M2, T cell CD4+ naïve, Tregs, monocyte, neutrophil, and NK activated, differed significantly between the different risk subgroups." (PMID 35592707, 2022). "In contrast to Tregs, which are thought to enable tumor proliferation, Th17 cells are CD4+ T helper cells that prevent the expansion of malignant cells in the TME and modulate antitumor immune responses." (PMID 34417572, 2022). "A subpopulation of CD4+ T cells, the regulatory T cells (Tregs), is a key player in suppressing anti-tumor immunity." (PMID 36311724, 2022). "At diagnosis, there was only a scattered and CD4-dominated T lymphocyte infiltration within NC tumor sites." (PMID 36387105, 2022). "Studies have found that in tumor immunity, CD4+ T cells can activate CD8+ T cells through various mechanisms after being activated to differentiate into cytotoxic T-lymphocytes, while maintaining and enhancing their anti-tumor response." (PMID 35935838, 2022). "Regarding T cells, host CD4 T cells were significantly increased in tumor-bearing mice compared to naive F1 controls." (PMID 35795681, 2022). "In CCA, patients with intraepithelial tumor-infiltrating CD4-, CD8-, and FOXP3-T lymphocytes showed a significantly longer overall survival." (PMID 35267462, 2022). "CD4+ helper T (Th) cells are mainly involved in tumor immunology, and can be functionally subdivided into different subgroups, namely Th1, Th2 and Th17 cells, according to the secretion of cytokines and immune function." (PMID 36276981, 2022). "The tumor microenvironment of LUAD pathogenesis was influenced by CD4 + T cells, type 1 regulatory T cells, and T helper 1 cells." (PMID 35918384, 2022). "In another recent study, the CD8+ and CD4+ tumor-infiltrating lymphocyte compartment was characterized in depth." (PMID 36539408, 2022). "Among the three clusters, cluster 2 had a higher immune score and a significantly higher abundance of CD8 T cells and activated memory CD4 T cells were assigned as a hot tumor, while cluster 1 and 3 were assigned as a cold tumor." (PMID 35677557, 2022). "We demonstrated that liposomal SNA enhanced activation of dendritic cells (DCs), promoted expansion of CD8+ and CD4+ T cells in both tumors and spleen, inhibited tumor growth, and extended animal survival." (PMID 35303868, 2022). "Repression of EZH2 in tumor-infiltrating Treg cells thus promote pro-inflammatory signaling and enhance recruitment of CD8+ and CD4+ effector T cells, ultimately leading to tumor regression." (PMID 35438143, 2022). "CTLs primed in concomitance with CD4 T cell help provided by the T-helper epitope display increased expansion potential and the highest ability of protecting from tumor growth." (PMID 35739113, 2022). "For example, cluster C1_CD4 contained mainly cells from blood, whereas clusters C8,9,10,11_CD8 and C12_CD4 were almost exclusively populated with cells from tumor tissue." (PMID 35668194, 2022). "Our results identify CD39 expression as a surrogate marker of circulating helper tumor-Ag-specific CD4 T cells." (PMID 35954341, 2022). "One of the unanswered questions that still needs to be addressed is how the MDV CD4+ T cells are pushed into latency and what determines which of these cells transform into tumor cells." (PMID 36146821, 2022). "According to the results of the TIMER database, PSENEN expression was significantly and positively correlated with six tumor-infiltrating immune cells (B cells, CD4 + T cells, CD8 + T cells, macrophages, neutrophils, and dendritic cells) in LGG." (PMID 35966015, 2022).